USP38 (ubiquitin specific peptidase 38)
Description:
Deubiquitinating enzyme that plays a role in various cellular processes, including DNA repair, cell cycle regulation, and immune response. Plays a role in the inhibition of type I interferon signaling by mediating the 'Lys-33' to 'Lys-48' ubiquitination transition of TBK1 leading to its degradation. Cleaves the ubiquitin chain from the histone demethylase LSD1/KDM1A and prevents it from degradation by the 26S proteasome, thus maintaining LSD1 protein level in cells. Plays a role in the DNA damage response by regulating the deacetylase activity of HDAC1. Mechanistically, removes the 'Lys-63'-linked ubiquitin chain promoting the deacetylase activity of HDAC1 in response to DNA damage. Also acts as a specific deubiquitinase of histone deacetylase 3/HDAC3 and cleaves its 'Lys-63'-linked ubiquitin chains to lower its histone deacetylase activity. Regulates MYC levels and cell proliferation via antagonizing ubiquitin E3 ligase FBXW7 thereby preventing MYC 'Lys-48'-linked ubiquitination and degradation. Participates in antiviral response by removing both 'Lys-48'-linked and 'Lys-63'-linked polyubiquitination of Zika virus envelope protein E. Constitutively associated with IL-33R/IL1RL1, deconjugates its 'Lys-27'-linked polyubiquitination resulting in its autophagic degradation.
Synonyms: KIAA1891; HP43.8KD
Tractability: PROTAC: ubiquitination databases record sites on it.
Gene: Protein-coding gene on chromosome 4 (143,184,917 to 143,225,212, forward strand). Ensembl gene ENSG00000170185.
Subcellular location: Cytoplasm; Nucleus
Subcellular location (Human Protein Atlas): Nucleoplasm; Centrosome; Cytosol
Gene Ontology:
Molecular function: cysteine-type deubiquitinase activity; protein binding
Biological process: negative regulation of innate immune response; negative regulation of proteasomal ubiquitin-dependent protein catabolic process; protein K33-linked deubiquitination; protein deubiquitination; ubiquitin-dependent protein catabolic process
Cellular component: cytoplasm; nucleus
Genetic constraint (gnomAD): Loss-of-function variants: 43 observed, 86.44 expected, observed/expected ratio (o/e) 0.5, 90% interval 0.39 to 0.64. The upper end of that interval is the gene's LOEUF score, 0.64, which puts it in group 2 of 6, group 1 being the genes least tolerant of losing a copy. Missense variants: 1,087 observed, 1,228.9 expected, observed/expected ratio (o/e) 0.88, 90% interval 0.84 to 0.93. Synonymous variants: 447 observed, 467.77 expected, observed/expected ratio (o/e) 0.96, 90% interval 0.88 to 1.03.
Homologues: Orthologues: chimpanzee USP38 (99% identical), macaque USP38 (98% identical), rabbit USP38 (94% identical), pig USP38 (93% identical), guinea pig USP38 (92% identical), mouse Usp38 (90% identical), dog USP38 (90% identical), rat Usp38 (89% identical), tropical clawed frog usp38 (73% identical), zebrafish usp38 (62% identical). Paralogues in human: USP35 (43% identical), USP34 (22% identical), USP9X (18% identical), USP9Y (17% identical), USP24 (17% identical), USP32 (16% identical), USP19 (15% identical), USP8 (15% identical), USP4 (14% identical), USP15 (14% identical), USP11 (13% identical), USP16 (13% identical), and 59 more.
Diseases named in the same sentence as USP38 in open-access papers:
USP38 is named in the same sentence as 45 diseases in open-access papers, as found by Europe PMC text mining. Sharing a sentence is not in itself a finding about the gene and the disease. The quoted sentences say what the papers report.
asthma (10 papers, 2014 to 2025). "Another study demonstrated that USP38 specifically targets Th2 immunity and the associated asthma via removing the K48-linked polyubiquitination of JunB26." (PMID 38481817, 2024). "Current research has linked USP38 to the development of many diseases such as asthma, pulmonary fibrosis, and colorectal cancer." (PMID 36845374, 2023). "According to the currently reported genome-wide association studies (GWAS), the LD block region including rs1397527 and containing the USP38/GAB1 genes has been identified as a susceptibility locus for adult asthma in the Japanese population." (PMID 38057792, 2023). "SNPs in USP38 have been associated with susceptibility to asthma, but the gene lies in a 700-kb region close to malaria candidates in the GYP-E/A/B gene cluster as well as the SMARCA5 and FREM3 loci." (PMID 25805752, 2015). "USP38 is a deubiquitinating enzyme and was recently identified as a susceptibility gene for asthma." (PMID 25432663, 2014). "In recent years, although studies have explored the regulatory roles of USP38 in various diseases, including cardiovascular diseases, asthma, and inflammatory responses, most research has focused on its role in malignant tumors." (PMID 40936898, 2025). "USP38 promoted asthma pathogenesis by stabilizing JunB protein and was the first identified DUB specific to the Th2 immune response." (PMID 40893770, 2025). "Subsequently, in 2011, Tomomitsu Hirota and colleagues identified USP38 as part of a genetic susceptibility region shared with the GAB1 gene, which is associated with susceptibility to adult asthma in Japan." (PMID 40936898, 2025). "In contrast to our expectation, 6 asthma SNPs showed nominal association with lower eosinophil counts in the general population (rs1233578 [ZBED9], rs519973 [BCL6], rs7686660 [USP38], rs6691738 [TNFSF4], rs2507978 [HLA‐B], rs3117098 [HCG23]), and 1 SNP in the asthma population (rs2786098 [CRB1])." (PMID 37186423, 2023). "USP38 might be a potential target for Th2 immune response and related asthma therapy." (PMID 40893770, 2025). "Ubiquitin-specific peptidase 38 (USP38) is a member of ubiquitin-specific processing enzymes family, and it has been reported that it inhibits type I IFN signaling during viral infection, which is also associated with some diseases, such as ciliopathies and asthma." (PMID 34696459, 2021). "Functionally, USP38 was necessary for production of Th2 cytokines (IL-4, IL-5 and IL-13) induced by TCR, and mice with USP38 knockout were refractory to asthma induced by OVA or HDM." (PMID 37731821, 2023).
ZIKV infection (5 papers, 2021 to 2025). "USP38 was capable to attenuate both K48- and K63-linked ubiquitination of E protein to prevent ZIKV infection." (PMID 34696459, 2021). "Here, we demonstrate that, overexpression of USP38 in Hela cells markedly inhibited ZIKV infection, while deficient of USP38 increased ZIKV invasion." (PMID 34696459, 2021). "So far, to the best of our knowledge, there is no inhibitor that makes use of this pathway, suggesting that USP38 is a potential novel target against ZIKV infection." (PMID 38543732, 2024). "It has been evident that HeLa cells overexpressing USP38 significantly reduced the ubiquitination of E protein, thus inhibiting ZIKV infection." (PMID 39273370, 2024). "The results revealed that the USP38 (C454S/H857A/D918N) mutant failed to remove polyubiquitination of E, and it also abolished the inhibitory effect of USP38-mediated ZIKV infection." (PMID 34696459, 2021). "Taken together, these results demonstrate that deubiquitinating activity of USP38 is required for the function of USP38 in the repression of ZIKV infection." (PMID 34696459, 2021). "Finally, USP38, a ubiquitin-specific peptidase, has been identified as a host restriction factor in resisting ZIKV infection by removing the ubiquitination of the viral E protein, which is critical for ZIKV infection and transmission." (PMID 40573410, 2025). "In conclusion, these data proved that USP38 was responsible for the restriction of ZIKV infection." (PMID 34696459, 2021). "We speculated that deubiquitinase activity of USP38 may play an important role in the restriction of ZIKV infection." (PMID 34696459, 2021). "Based on our data, we proposed the molecular mechanism of USP38 against ZIKV infection." (PMID 34696459, 2021). "Here, we initially explored the role of USP38 in ZIKV infection." (PMID 34696459, 2021). "To further prove whether the enzyme activity of USP38 was essential for its inhibition of ZIKV infection; we constructed a USP38 mutant (C454S/H857A/D918N) that has lost deubiquitination enzyme activity." (PMID 34696459, 2021). "Next, the mechanism by which USP38 represses ZIKV infection was explored." (PMID 34696459, 2021). "USP38 has been found to inhibit type-I IFN signaling during viral infection, playing an important role in host resistance to ZIKV infection." (PMID 39273370, 2024). "In this article, we discovered a novel host protein, USP38, which bound to ZIKV E protein and removed polyubiquitination of E protein to resist ZIKV infection." (PMID 34696459, 2021). "Several host cellular factors restrict ZIKV infection, including LAMR1 (Laminin receptor 1), Hpa (heparanase), Viperin, and USP38 (Ubiquitin-specific peptidase 38), which target different stages of the viral life cycle, such as entry, replication, and protein stability." (PMID 40573410, 2025). "Overexpression of USP38 (ubiquitin-specific peptidase 38) in HeLa cells, which is also known to regulate inflammation and histone modification and can inhibit IFN-I signaling during viral infection, reduced ZIKV infection." (PMID 36151059, 2023). "Here, our data suggested that the ubiquitin-specific peptidase 38 (USP38) played an important role in host resistance to ZIKV infection, during which ZIKV infection did not affect USP38 expression." (PMID 34696459, 2021). "In conclusion, we found a novel host protein USP38 against ZIKV infection, and this may represent a potential therapeutic target for the treatment and prevention of ZIKV infection." (PMID 34696459, 2021). "In addition, we found that the deubiquitinase activity of USP38 was essential to inhibit ZIKV infection, and the mutant that lacked the deubiquitinase activity of USP38 lost the ability to inhibit infection." (PMID 34696459, 2021). "Furthermore, immunofluorescence analyses indicated that the levels of ZIKV dsRNA were repressed by USP38, but not by the mutant protein, suggesting that unlike USP38, the mutant protein USP38-MUT failed to repress ZIKV infection." (PMID 34696459, 2021).
colorectal cancer (4 papers, 2019 to 2025). A primary or metastatic malignant neoplasm that affects the colon or rectum. "To dissect the underlying mechanism of how USP38 regulates colorectal cancer cell growth, we analyzed the cancer stem cells properties of colorectal cancer cells with downregulated, normal and upregulated levels of USP38." (PMID 32404892, 2020). "In colorectal cancer, overexpression of USP38 can activate downstream tumor-suppressive signaling pathways by promoting the expression of key regulatory factors such as HMX3 and HDAC3." (PMID 40936898, 2025). "It is noteworthy that, in contrast to the positive regulatory role of USP38 in malignancies such as gastric and colorectal cancers, USP38’s suppression of JAK2/STAT3 signaling pathway activation in glioma demonstrates its dual role in tumor regulation." (PMID 40936898, 2025). "The positive regulatory effect of USP38 on HMX3 expression indicates that in colorectal cancer, USP38 can influence tumor cell growth by regulating multiple signaling pathways (such as the USP38/HDAC3 signaling axis and the USP38/LSD1 signaling axis)." (PMID 40936898, 2025). "Our results showed that downregulation of USP38 significantly promoted the colony formation capacity of colorectal cancer cells suggesting that USP38 inhibits the growth of colorectal cancer cells." (PMID 32404892, 2020). "To evaluate the role of USP38 in colorectal cancer, we first analyzed the expression levels of USP38 in clinical colorectal cancer samples and respective adjacent tissues." (PMID 32404892, 2020). "More importantly, we found that the expression of USP38 was negatively correlated with the expression of CD133, CD44, and SOX2 suggesting that USP38 negatively regulates cancer stem cells in colorectal cancer patients." (PMID 32404892, 2020). "To understand how the aberrant USP38 expression affects human colorectal cancer, we next interfered the residual USP38 expression with shRNA (small hairpin RNA) targeting USP38." (PMID 32404892, 2020). "We analyzed the colony formation capacity of colorectal cancer cells transfected with control shRNA or shRNA targeting USP38." (PMID 32404892, 2020). "Since cancer stem cell population is critical for chemoresistance, we next examined the responses of colorectal cancer cells with altered USP38 expression to chemotherapeutics." (PMID 32404892, 2020). "Our work revealed a novel tumor suppressor function of USP38 in human colorectal cancer via directly regulating ubiquitination status of HDAC3." (PMID 32404892, 2020). "Since our data demonstrated a tumor suppressor role of USP38 in colorectal cancer patients, we then analyzed clinical samples to validate the clinical significance of USP38 in colorectal cancer patients." (PMID 32404892, 2020). "Here, we identified that an ubiquitin-specific protease (USP), USP38, was downregulated in clinical colorectal cancer samples and colorectal cancer cell lines." (PMID 32404892, 2020). "Moreover, we have provided information on the expression level of USP38 in different stages of colorectal cancer and showed that high level of USP38 indicated a better overall survival suggesting that USP38 may have the potential of serving as a diagnostic marker for colorectal cancer staging." (PMID 32404892, 2020). "Meanwhile, USP38 overexpression resulted in reduction of cancer stem cell marker genes which further indicated that USP38 prohibits stemness of colorectal cancer cells." (PMID 32404892, 2020). "Our work revealed that USP38 is a novel player in regulating stemness of colorectal cancer." (PMID 32404892, 2020). "Importantly, our results showed that downregulation of USP38 significantly facilitated the tumorigenesis of colorectal cancer cells and vice versa." (PMID 32404892, 2020). "Hence, targeting USP38 as well as HDAC3 are promising strategy in overcoming chemoresistance of colorectal cancer." (PMID 32404892, 2020).
colorectal cancer (continued). "Moreover, the number of colorectal cancer cells transfected with shRNA targeting USP38 was significantly higher than that of colorectal cancer cells transfected with control shRNA after 120 h of culture." (PMID 32404892, 2020). "Therefore, with both in vitro and in vivo data, we conclude that USP38 inhibits growth of colorectal cancer cells." (PMID 32404892, 2020). "In addition, our results demonstrated a tumor suppressor role of USP38 in colorectal cancer via inhibiting cancer stem cell populations." (PMID 32404892, 2020). "Hence, our data indicated that downregulation of USP38 further facilitates the growth of colorectal cancer cells." (PMID 32404892, 2020). "Our results showed that both mRNA levels and protein levels of USP38 were significantly decreased in colorectal cancer samples compared to adjacent tissues suggesting a tumor suppressive role of USP38 in human colorectal cancer." (PMID 32404892, 2020). "Hence, our data illustrated that USP38 is downregulated in human colorectal cancer." (PMID 32404892, 2020). "Hence our data suggested that USP38 restrains cancer stem cell population in colorectal cancer." (PMID 32404892, 2020). "Our data provided functional insights of USP38 and HDAC3 in colorectal cancer and revealed novel mechanisms of ubiquitination mediated epigenetic regulation." (PMID 32404892, 2020). "In colorectal cancer, further analysis of the TCGA dataset reveals a negative correlation between USP38 expression and tumor malignancy." (PMID 40936898, 2025).
viral infection (4 papers, 2021 to 2023). "Ubiquitin-specific peptidase 38 (USP38), a member of the ubiquitin specific processing enzyme family, has been reported to inhibit type I interferon signaling during viral infection." (PMID 35602051, 2022). "Subsequently, it was revealed that USP38 played a role in virus immunity by inhibiting the IFN-I pathway in the case of virus infection." (PMID 34696459, 2021). "Previous studies determined that, during viral infection, USP38 inhibits type I interferon pathway by degrading TBK1, thereby inhibiting the synthesis of type I IFN." (PMID 34696459, 2021). "In conclusion, we revealed a new function of USP38 in viral infection and this may provide a new potential therapeutic target for ZIKV-associated diseases." (PMID 34696459, 2021).
atrial fibrillation (3 papers, 2023 to 2025). A disorder characterized by an electrocardiographic finding of a supraventricular arrhythmia characterized by the replacement of consistent P waves by rapid oscillations or fibrillatory waves that vary in size, shape and timing and are accompanied by an irregular ventricular response. "CKD mice exhibited increased AF inducibility relative to sham controls, and USP38 significantly altered atrial fibrillation susceptibility in CKD mice." (PMID 40514673, 2025). "This study aimed to elucidate the role of the deubiquitinase USP38 in chronic kidney disease (CKD)-associated atrial fibrillation (AF) by investigating its impact on atrial structural and electrical remodeling and its interaction with STRAP and TGF-β/SMAD signaling." (PMID 40514673, 2025).
bladder cancer (3 papers, 2022 to 2025). "The positive feedback loop mediated by USP38 effectively inhibits the malignant progression of bladder cancer, underscoring its important role in the regulatory mechanism of METTL14." (PMID 40936898, 2025). "The reciprocal regulatory circuit between METTL14 and USP38 can promote EMT in bladder cancer." (PMID 40986143, 2025). "However, in clear cell renal carcinoma and bladder cancer cell lines, knockdown of USP38 actually promotes tumor cell proliferation, indicating that the expression level of USP38 varies across different tumor cell lines." (PMID 40936898, 2025). "Moreover, targeting both USP38 and METTL14 in therapy could theoretically enhance the inhibition of bladder cancer tumor cells, offering new insights and recommendations for targeted treatment of bladder cancer." (PMID 40936898, 2025).
colitis (3 papers, 2020 to 2023). Inflammation of the colon. "in addition, they induced acute colitis in mice by dextran sodium sulfate(DSS) model, USP38-KO mice were more susceptible to DSS-induced colitis, with increased colonic inflammation and higher mortality." (PMID 37953295, 2023). "Knockout (KO) of Usp38 in mice causes excessive inflammatory responses which enhance the symptoms of acute colitis and lung injury in response to endotoxin shock." (PMID 33240782, 2020). "Loss of Usp38 in mice markedly enhances susceptibility to endotoxin shock and acute colitis, and these mice display a more severe inflammatory phenotype compared to wild‐type mice." (PMID 33240782, 2020). "USP38 knockout mice showed more severe signs of inflammatory response in acute colitis and lung injury induced by endotoxic shock." (PMID 36845374, 2023). "Collectively, these results highlight a crucial role for USP38‐regulated cytokines in protection against the development of inflammation‐induced colitis in bone marrow‐derived cells." (PMID 33240782, 2020). "To further confirm whether these USP38‐regulated cytokines are responsible for the DSS‐induced colitis in USP38‐KO mice, we neutralized IL‐6 and IL‐23 by peritoneal injection of anti‐IL‐6/IL‐23 antibodies (Abs) in WT or USP38‐KO colitis mice." (PMID 33240782, 2020).